LINC01363 (long independently transcribed non-coding RNA 1363)
Synonyms: RBSG4
Gene: Long non-coding RNA gene on chromosome 1 (167,175,363 to 167,195,792, reverse strand). Ensembl gene ENSG00000231605.
Diseases named in the same sentence as LINC01363 in open-access papers:
LINC01363 is named in the same sentence as 2 diseases in open-access papers, as found by Europe PMC text mining. Sharing a sentence is not in itself a finding about the gene and the disease. The quoted sentences say what the papers report.
cervical cancer (1 paper, 2021). A primary or metastatic malignant neoplasm involving the cervix. "LINC01363, which is related to worse prognosis, has been shown to be upregulated in breast, ovarian, and cervical cancer." (PMID 33499129, 2021).
Obesity (1 paper, 2019). Accumulation of substantial excess body fat. "Within the first locus, RBGS4, also known as LINC01363, encodes a long non-coding RNA (lncRNA) and has not been previously reported to associate with obesity and weight loss interventions." (PMID 30710084, 2019).